FAP (fibroblast activation protein alpha)
Diseases named in the same sentence as FAP in open-access papers (continued):
Sharing a sentence is not in itself a finding about the gene and the disease.
Myocardial fibrosis (13 papers, 2023 to 2026). "Studies from the University of Pennsylvania in 2019 and 2022 demonstrated that CAR-T cells can effectively target and eliminate FAP-expressing myoFbs, thereby inhibiting myocardial fibrosis." (PMID 40977952, 2025). "Ex vivo analysis of cardiac tissue indicated that, despite substantial myocardial fibrosis, FAP expression was relatively lower in animals with 3 d of rest." (PMID 40935615, 2025). "Myocardial fibrosis is driven by the activation of fibroblasts; in this sense, FAP has recently been proposed as a marker that exclusively identifies activated fibroblasts, allowing noninvasive quantitative measurement of early cardiac remodeling." (PMID 38297310, 2024). "Myocardial fibrosis and cardiac remodeling are known as the pathological hallmarks of DCM, and the association of hub genes (MFAP4, ASPN, and FAP) with fibrosis and cardiac remodeling has been identified in prior research." (PMID 37869159, 2023). "Pharmacological inhibition of FAP was also previously shown to mitigate myocardial fibrosis." (PMID 40384987, 2025). "Recently,radiolabeled molecular probe targeting FAP, represented by 68Ga-FAPI PET,has been able to detect the activity of myocardial fibrosis in HFpEF by bindingto FAP expressed on activated fibroblasts." (PMID 41209131, 2025). "With the development of small-molecule FAP inhibitors such as 18F-labeled AlF-FAPI, research on the relationship between the abnormality of ventricular wall motion and the alteration of myocardial fibrosis has become feasible using PET imaging technology." (PMID 40138865, 2025). "Continuing with FAP as the target, we investigated the potential of CAR-T cells in treating myocardial fibrosis, expecting further evidence to support CAR-T cell therapy as a viable strategy for its inhibition." (PMID 40977952, 2025). "Runx1 expression was also observed in cardiac fibroblasts along with genes contributing to myocardial fibrosis, such as POSTN, MEOX1 and FAP, and its expression was also negatively correlated to ejection fraction." (PMID 38862712, 2024). "In this study, we found that FAP is significantly increased after PAB and correlates with myocardial fibrosis detected by RV pathological staining." (PMID 37932744, 2023). "Given the emerging potential of CAR-T therapy in nononcological diseases and FAP as a therapeutic target for myocardial fibrosis, we engineered a second-generation FAP-targeted CAR with the 4-1BB costimulatory domain to enhance safety and persistence." (PMID 40977952, 2025). "IL-17-treated hCOs faithfully mimicked human myocardial fibrosis, and human FAP.CAR-T cells effectively cleared FAP+ cells without harming cardiomyocytes." (PMID 41356193, 2026). "In comparison, inhibition of FAP by 177Lu‐FAPI showed no significant side effects at the current dose and may thus be a safer approach for improving cardiac function and reducing myocardial fibrosis post‐MI." (PMID 40384987, 2025).
oral squamous cell carcinoma (13 papers, 2016 to 2025). "DPP9 interacts with FAP directly in oral squamous cell carcinoma, and DPP9 overexpression can inhibit the epithelial-mesenchymal transition activity induced by FAP." (PMID 39876559, 2025). "Tumor promotion induced by FAP via epithelial-mesenchymal transition (EMT) was observed in oral squamous cell carcinoma (OSCC)." (PMID 39579201, 2024). "The PTEN/PI3K/AKT and Ras-ERK signaling pathways have been shown to be strongly inhibited in oral squamous cell carcinoma when FAP is suppressed." (PMID 37752545, 2023). "Other studies on oral squamous cell carcinoma have indicated that FAP is an upstream regulator of phosphatase and tensin homolog PI3K/protein kinase B and Ras-ERK signaling pathways." (PMID 34490078, 2021). "Knockdown of FAP in oral squamous cell carcinoma cells reduce the migration and invasion through Matrigel40." (PMID 34035230, 2021). "The knockdown of DPP9 in oral squamous cell carcinoma cells increased cell growth via FAP-α, whereas the overexpression of DPP9 in Huh-7 and HepG2 cells reduced proliferation and increased apoptosis independent of its enzymatic activity by interacting with HRAS." (PMID 37626841, 2023). "Other studies have indicated that FAP was highly expressed in oral squamous cell carcinoma cells, where FAP gene knockout inhibited tumor cell proliferation, migration, and invasion through the inhibition of the phosphatase and tensin homolog/PI3K/protein kinase B and Ras-ERK signaling pathways." (PMID 34490078, 2021). "As for FAP, it is one of the active members of the S9b protease family and known to promote EMT of oral squamous cell carcinoma (OSCC)." (PMID 35910202, 2022). "A previous study showed that inhibition of FAP expression reduces cell adhesion, migration, invasion, and metastatic capacity, while inducing EMT in oral squamous cell carcinoma." (PMID 32639951, 2020).
Lewis lung carcinoma (12 papers, 2012 to 2025). "The first experiments that assessed the immunologic effects of perturbing the FAP α+ stromal cells used a direct approach of conditionally depleting this cell type from a mouse bearing immunogenic Lewis lung carcinoma cells expressing ovalbumin (LL2/OVA)." (PMID 26985769, 2016). "Genetic deletion of FAP leads to a marked reduction in FAP+ CAF infiltration and rapid hypoxic necrosis of tumor and is associated with increased CD8+ T cells infiltration in Lewis lung carcinoma and PDAC models." (PMID 31462327, 2019). "Importantly, we detected FAP on tumor-infiltrating CD11b+ cells, especially by M- and PMN-MDSC, as well as CD11b+ cells that did not express Ly6C and -G, probably tumor-associated macrophages (TAM), as has been shown in tumors of Lewis lung carcinoma." (PMID 36230765, 2022). "In order to determine the role of FAP α-expressing stromal cells in immune suppression within the TME, a transgenic mouse model has been created with established Lewis lung carcinomas." (PMID 26985769, 2016).
keloid (11 papers, 2015 to 2025). An irregularly shaped, elevated mark on the skin caused by deposits of excessive amounts of collagen during wound healing. "Studies of skin system disorders show that high expression of FAP directly or indirectly increases the invasive ability of keloid fibroblasts, and that selective inhibition of FAP leads to reduced invasion." (PMID 37006278, 2023). "The FAP expression level is enhanced in keloid fibroblasts and FAP modulation has been shown to attenuate the invasiveness of scars." (PMID 37033989, 2023). "The inhibition of FAPα by H2N-Gly-Pro diphenylphosphonate (FAPα/DPPIV inhibitor) in keloid fibroblasts reduces their invasive activity to near normal levels without affecting the invasiveness of normal fibroblasts." (PMID 38136590, 2023). "In the article by Dienus, it was shown that fibroblasts isolated from an actively growing margin of keloid scars had a significantly high level of FAPα protein and invaded three times better than fibroblasts from normal areas of the skin." (PMID 38136590, 2023). "As in the development of tumor pathologies, the prolonged expression of FAPα promotes the invasive growth of fibroblasts in fibroproliferative conditions such as keloids, and FAPα expression is increased eightfold in the deepest part of the keloid compared with that in healthy skin." (PMID 38136590, 2023). "Fibroblast activation protein alpha (FAP) is a plasma membrane serine protease (dipeptidyl peptidase IV) that may play a key role in the invasiveness of keloids." (PMID 36092734, 2022). "In this study, we discovered that the induction of FAP expression by electron beam only in the primary human keloid derived fibroblast, we also attempted to detect radiation-induced FAP expression in mouse fibroblast cell line, but the cell line displayed a poor radio-sensitivity (data not shown)." (PMID 36092734, 2022). "FAP expression is observed in keloid and in the physiological process of wound healing." (PMID 36531015, 2022). "Additionally, higher expression of CD26 and FAP fibroblasts was observed in keloids." (PMID 39056788, 2024). "This “dual‐locked” design strategy guarantees the specific activation of FC‐1 in the presence of both FAPα and CTSC, thereby enabling precise differentiation between cSCC tissues and keloid tissues." (PMID 41035512, 2025). "Importantly, 16S rRNA co-localizes with immunostaining of fibroblast activation protein alpha (FAP), the marker of fibroblasts in keloids." (PMID 39081787, 2024). "The use of a FAPα inhibitor on isolated keloid fibroblasts reduced their invasion but did not influence procollagen I and fibronectin synthesis." (PMID 39364020, 2024).
lymphoma (11 papers, 2020 to 2026). A malignant (clonal) proliferation of B- lymphocytes or T- lymphocytes which involves the lymph nodes, bone marrow and/or extranodal sites. "In conclusion, while FAPI PET/CT exhibits lower diagnostic sensitivity than [18F]FDG PET/CT in lymphomas characterized by low FAP expression, it retains potential as a complementary imaging modality." (PMID 40417720, 2025). "The systematic review reveals that FAPI PET/CT exhibits lower diagnostic sensitivity than [18F]FDG PET/CT in lymphomas characterized by low FAP expression." (PMID 40417720, 2025). "Future research should focus on further elucidating the mechanistic basis of FAP regulation in lymphoma and evaluating the therapeutic potential of targeting FAP in combination with other treatments." (PMID 41373408, 2025). "Future studies should aim to delineate the contributions of these different FAP activities in lymphoma and assess the therapeutic potential of targeting both enzymatic and non-enzymatic functions." (PMID 41373408, 2025). "Similar findings were previously reported by other studies, showing higher FAP expression in aggressive lymphomas compared to indolent subtypes." (PMID 41373408, 2025). "Lymphoma FRCs can exhibit CAFs like immunophenotypes, including FAP, α-SMA, and upregulation of immune regulatory MHC class I, PD-L1, and PD-L2 molecules." (PMID 40626005, 2025). "In conclusion, [68Ga]FAPI PET/CT can effectively detect FAP in lymphoma lesions, potentially serving as an additional tool to characterize lymphomas." (PMID 40417720, 2025). "A recent study has shown that 68Ga-FAPI imaging can be used to detect FAP expression in lymphoma lesions." (PMID 40484962, 2025). "This study aimed to investigate the level and activity of soluble FAP (sFAP) in pre-therapeutic serum samples from 120 lymphoma patients." (PMID 41373408, 2025). "GLUT1 and hexokinase 2 were overexpressed in lymphoma cells and the microenvironment, while FAP was stromal." (PMID 40417720, 2025). "Another pivotal study compared [68Ga]FAPI and [18F]FDG PET/CT in lymphoma, examining FAP and glycolytic marker uptake." (PMID 40417720, 2025). "Combining FAP-targeted treatments with immunotherapy warrants further exploration to improve lymphoma outcomes." (PMID 41373408, 2025). "Immunohistochemistry staining results showed that hexokinase 2 (HK2) and glucose transporter 1 (GLUT1) cell densities were significantly higher than FAP in most lymphoma subtypes (p < 0.001)." (PMID 39595051, 2024). "However, several previous studies have demonstrated that 68Ga-FAPI PET/CT has poorer diagnostic efficacy than fluorine 18 (18F) labeled fluorodeoxyglucose (18F-FDG) PET/CT for lymphoma, especially those with low FAP expression." (PMID 40484962, 2025). "Whereas 68Ga-FAPI targets fibro-activating proteins and therefore may account for the better response to treatment in lymphomas with high FAP uptake." (PMID 40484962, 2025). "While we measured sFAP activity and concentration in serum, further investigations are required to determine whether tissue-specific forms of FAP also play a role in lymphoma pathogenesis." (PMID 41373408, 2025). "This may be because lymphomas with higher FAP expression are more aggressive, whereas high-grade lymphomas are usually responded well to chemotherapy." (PMID 40484962, 2025). "This may be related to the highly dynamic and variable tumor microenvironment in aggressive lymphomas, where rapid proliferation, immune evasion, and stromal remodeling may alter the balance of proteolytic enzymes like FAP." (PMID 41373408, 2025). "68Ga-FAPI imaging may be an alternative method for detecting FAP expression in lymphoma lesions and characterizing lymphoma profiles." (PMID 34858834, 2021). "It is suggested that monitoring FAP expression may be a way to characterize lymphoma." (PMID 40626005, 2025). "However, its sensitivity is lower in lymphomas with minimal stromal FAP expression." (PMID 40417720, 2025).
lymphoma (continued). "Although the vast majority of neuroectodermal tumors, carcinomas, and lymphomas were found to be FAP negative, expression was observed in the reactive stroma that surrounds many of these tumors, suggesting that FAP has a role in mesenchymal activation." (PMID 40542914, 2025). "To explore potential correlation between sFAP serum level and FAP tumor tissue expression, we assessed the protein expression levels within lymphoma biopsies from the subgroups of DLBCL (n = 23) and FL (n = 11) patients from whom a pre-therapeutic lymphoma tissue sample was available." (PMID 41373408, 2025). "However, FAP was expressed in some lymphomas without HK2 and/or GLUT1." (PMID 39595051, 2024).
renal cell carcinoma (11 papers, 2020 to 2026). "FAP PET has been suggested as a promising new diagnostic tool to address the limitations of previously available imaging modalities in renal cell carcinoma (RCC)." (PMID 41101974, 2026). "For instance, FAP+ fibroblast signatures in renal cell carcinoma serve as potential biomarkers for predicting patient prognosis and resistance to anti-VEGF therapy." (PMID 41303611, 2025). "Nonetheless, a consistent pattern emerged: head and neck, breast, lung, and esophageal tumors exhibited the highest FAP expression, whereas renal cell carcinoma (RCC) demonstrated low levels." (PMID 38558814, 2024). "We studied the in vivo activity of IL2-7NP2-TNFmut (directed to tumor cells) and IL2-F8-TNFmut (directed to the tumor neovasculature and stroma) in a xenograft model of renal cell carcinomas overexpressing human FAP on the cell surface." (PMID 37092450, 2023). "FAP expression was higher in cancers of the bile duct, bladder, colon, esophagus, stomach, lung, oropharynx, ovary, and pancreas; average in breast and uterus cancer; and liver, prostate, and renal cell cancer showed only low FAP expression." (PMID 35327325, 2022). "Liver, prostate, and renal cell cancer were the 3 tumor types with the lowest FAP expression." (PMID 34740953, 2022). "Renal cell carcinoma (not shown) had a lower level of association which could potentially be attributed to the overall diminished levels of FAP expression in RCC tumors combined with the limited availability of samples with matched results for IHC and RNAseq." (PMID 38558814, 2024). "Renal cell carcinomas (CCRCC, PRCC, and ChRCC) showed similar percentages of FAP positive staining, whereas all the benign tumours (ROs) were negative." (PMID 33207686, 2020). "Although our data do not favor FAP-based theranostic approaches in renal cell carcinoma, studies in larger cohorts are warranted for conclusive evidence." (PMID 41101974, 2026). "FAP-negative tumor phenotypes have also previously been described in the literature, e.g., in differentiated thyroid carcinoma and renal cell cancer." (PMID 34137945, 2021).
cholangiocarcinoma (10 papers, 2021 to 2025). A carcinoma that arises from the intrahepatic biliary tree (intrahepatic cholangiocarcinoma) or from the junction, or adjacent to the junction, of the right and left hepatic ducts (hilar cholangiocarcinoma). "Because of an abundant tumor stroma whose main cellular components are cancer-associated fibroblasts, cholangiocarcinoma is a promising tumor entity for 68Ga-FAP inhibitor (FAPI)-46 PET imaging." (PMID 37024301, 2023). "High 68Ga-FAPI-46 uptake and strong immunohistochemical FAP expression support the future evaluation of FAP RLT in patients with advanced cholangiocarcinoma." (PMID 37024301, 2023). "Here, we aimed to assess the accuracy of PET/CT with the novel cancer fibroblast–directed 68Ga-fibroblast activation protein (FAP) inhibitor (FAPI)-46 tracer for cholangiocarcinoma staging and management guidance." (PMID 37024301, 2023). "The tumor-specific FAP expression, high stromal content in cholangiocarcinoma and good specificity and retention properties of 68Ga-FAPI-46 radioligand probably led to the observed superior TBR and detection rate." (PMID 37024301, 2023). "Immunohistochemistry showed high and very specific FAP expression in tumor stroma whereas GLUT1 was expressed mainly on cholangiocarcinoma tumor cells." (PMID 37024301, 2023). "Research revealed that FAP promoted the growth of intrahepatic cholangiocarcinoma through the recruitment of myeloid derived suppression cells." (PMID 35004767, 2021). "FAP was most significantly upregulated in kidney chromophobe (KICH) and cholangiocarcinoma (CHOL) tissues." (PMID 40433364, 2025). "Our data reveals a significant correlation between FAP expression and pathological stage in seven tumors, including HNSC, KIRC, cholangiocarcinoma (CHOL), LAML, STAD, thymoma (THYM), and UCEC." (PMID 37490719, 2023). "Previous publications without a systematic histopathologic workup indicated FAP-directed PET to be highly accurate for the imaging of cholangiocarcinoma." (PMID 37024301, 2023). "Furthermore, we investigated immunohistochemical FAP and glucose transporter 1 (GLUT1) expression from tumor samples of our patient cohort and assessed the impact of 68Ga-FAPI-46 PET/CT on cholangiocarcinoma management." (PMID 37024301, 2023). "FAP targeting may become a valuable option for imaging and potentially RLT of cholangiocarcinoma." (PMID 37024301, 2023). "A patient suffering from cholangiocellular carcinoma that could not be clearly detected by conventional imaging, including a [18F]FDG-PET/CT, highlights the potential use of [68Ga]Ga-FAP-PET/CT." (PMID 39338305, 2024).
heart failure (10 papers, 2021 to 2026). Inability of the heart to pump blood at an adequate rate to meet tissue metabolic requirements. "The role of FAP as a diagnostic and therapeutic target in coronary artery disease is broadened to subsequent ischemic cardiomyopathy and heart failure." (PMID 40278373, 2025). "Collectively, these findings underscore the growing relevance of FAP inhibitor tracers in monitoring the progression of cardiac fibrosis and potentially guiding therapy in patients with various forms of heart failure." (PMID 40430477, 2025). "Collectively, these results further emphasize the value of FAP inhibitor tracers for monitoring cardiac fibrosis progression and guiding therapy for patients suffering from different entities of heart failure." (PMID 40430477, 2025). "Recently, promising data has been published on the development of anti-FAP CAR-T cells to treat cardiac fibrosis, demonstrating that effective elimination of FAP-positive cells from the injury site in a mouse model of heart failure improved cardiac compliance." (PMID 36531712, 2022). "This may reflect this type of heart failure, where collagen and FAP expression affects the heart in its entirety." (PMID 40430477, 2025). "Cardiac fibroblast activation protein (FAP) has an emerging role in heart failure (HF)." (PMID 38297310, 2024). "A longer study period extending 28 days post-MI might have shown a beneficial effect of genetic FAP deletion on symptoms of heart failure, ventricular rupture or mortality." (PMID 33667270, 2021). "Similar to SysHF HLHS fibroblasts, RVF fibroblasts displayed enriched levels of POSTN, FAP, FOS, and JUN, consistent with a preserved activated fibroblast population observed across human heart failure etiologies." (PMID 40502733, 2025).